IL4 (interleukin 4)
Diseases named in the same sentence as IL4 in open-access papers (continued):
Sharing a sentence is not in itself a finding about the gene and the disease.
melanoma (continued). "Melanoma exosomes have been shown to induce a spectrum of macrophage phenotypes secreting a variety of anti-inflammatory (IL-4, IL-10, IL-11, and IL-13) but also pro-inflammatory (TNF-α, IL-12B, IL-1β, IL-6, iNOS, and CCL22) factors, reflecting the spectrum of phenotypes detected in the TME." (PMID 38533720, 2024). "In addition, whereas the antitumor cytokines, like IFN-γ and TNF-α, in melanoma tissues increased, both IL-4 and IL-10 (pro-tumor cytokines) levels decreased at the end of the indicated treatment." (PMID 38491004, 2024). "Cytokines such as IL-4, IL-13, TGFβ, and IL-10 were most probably present in the melanoma-microglia interface and could have provided a variety of signals that led to divergent M1/M2 phenotypes." (PMID 37296634, 2023). "IL-2, IL-4, and IL-12 were the most widely used cytokines as vaccine adjuvants, especially IL-2, which was used as an immune adjuvant in many kinds of cancer types, such as lung cancer, colorectal cancer, and melanoma." (PMID 35967400, 2022). "IL-4 is found in various melanoma cells, including the human SK-MEL-28 and mouse B16F10 cell lines." (PMID 33959512, 2021). "In this sense, a rigorous follow‐up is recommended for early‐stage melanoma patients with a high Breslow thickness, high serum IL‐4 levels, and low GM‐CSF and DCD levels at the time of diagnosis, given the elevated risk for these patients to develop metastasis during follow‐up." (PMID 32485045, 2020). "Interestingly, elevated serum IL‐6 was correlated with a poor prognosis in melanoma, while IL‐4 is thought to promote the proliferation and survival of several cancer cells." (PMID 32485045, 2020). "Interestingly, in melanoma, steroidogenic gene expression was correlated with IL4 expression, a key inducer of T cell steroidogenesis." (PMID 32680985, 2020). "Il-4 was also shown to suppress cancer-directed-immunosurveillance and enhance tumor metastasis, while over-expression of IL-4 suppressed tumor development, tumor volume and weight in mice melanoma models." (PMID 31351482, 2019). "Indeed, both the culture supernatant of B16 melanoma cells and the tumor signature Th2 cytokine IL-4 significantly inhibited Trim24 expression in both mouse and human macrophages." (PMID 31554795, 2019). "We have previously reported that the addition of the heat shock-conditioned melanoma lysate TRIMEL to IL-4/GM-CSF-activated monocytes (AM) mediates the induction of canonical surface markers associated with DC maturation such as MHC I, MHC II, CD80, CD83, and CD86." (PMID 31886313, 2019). "For example, IL-4 directs regression of malignancies such as melanoma, glioma, and colon carcinoma." (PMID 29473868, 2018). "Thus, our data suggest that IL-4 suppresses tumor growth through p21-mediated activation of STAT6 in melanoma tumor of tissues." (PMID 26993600, 2016). "IL-4 inhibited cell growth of these cancer cells, and the most inhibition was found in melanoma." (PMID 26993600, 2016). "To identify the effect of IL-4 on tumor growth, we measured the tumor growth in a melanoma model." (PMID 26993600, 2016). "The highest expression of IL-4 and IL-4Rα was found in melanoma cells among the cancer cells." (PMID 26993600, 2016). "inoculation of IL-4-producing plasmacytoma, J558L or melanoma B16 cells." (PMID 25208941, 2014). "In the LLC carcinoma model, but not in the B16 melanoma model, the proinflammatory gene expression profile in the tumors collected from the ROS deficient mice was dominated by IL-4." (PMID 24358335, 2013). "Thus, our results showing IL-4 signaling alternation in melanoma patients is consistent with the notion that Th2 immune responses are associated with tumor promotion and progression." (PMID 21698244, 2011). "In addition, it has been documented that IL-13 and IL-4 downregulated arginase production in melanomas, leading to down-regulation of CD3ζ expression thus limiting T cell function." (PMID 20052413, 2010).
melanoma (continued). "It has already been shown that melanoma cells may express IL-4 receptors and that IL-4 has antiproliferative and/or apoptotic effects in these cells." (PMID 17129373, 2006). "Consistent with our in vitro findings, FL/GM-DCs exhibited significantly greater therapeutic efficacy than GM/IL4-DCs in both B16F10 melanoma and MC38 colorectal cancer models, whether applied as a tumor vaccine or as a therapeutic intervention after tumor onset." (PMID 40977690, 2025). "IL-4 contributes to the disease by affecting immune responses that may promote tumor progression and metastasis, thereby making it an important factor in prognostic evaluations for estimating the likelihood of metastasis in melanoma patients." (PMID 40636453, 2025). "Additionally, IL-4 and IL-13 from group 2 innate lymphoid cells suppressed antitumor immunity in a colorectal cancer model, and the production of IL-13 by group 2 innate lymphoid cells was upregulated by melanoma cells in vitro." (PMID 39598436, 2024). "Interleukin-4 and 13 signaling, thyroid cancer, pathways in cancer, signaling by interleukin, interleukin-10 signaling, melanogenesis, melanin biosynthesis, and tyrosine metabolism might be the key to treating melanoma." (PMID 36185647, 2022). "However, the ratio of IFN-γ+:IL-4+ B cells, a pro-inflammatory measure, which may represent the balance between Th1 (IFN-γ+) and Th2 (IL-4+) phenotypes, was significantly lower in melanoma patients compared to matched HV." (PMID 35909944, 2022). "Further, analysis of clusters identified within the melanoma patient set comparing patient outcome suggests that suppression of IL-1α, IL-4, IL-5, and CCL22, with concomitant elevation of CXCL10, CCL4, and CCL17, may correlate with more aggressive development of brain metastasis." (PMID 36527157, 2022). "We tested several combinations of cytokines expressed by LVs in DC precursors and showed that combined expression of GM-CSF and IL-4 was sufficient to promote their autonomous differentiation into highly viable human and murine DCs, capable to stimulate potent T cell responses against melanoma." (PMID 31628525, 2019). "Since IL-4 and IL-4Rα were highly expressed in melanoma cells, and melanoma cell growth has been known to be significantly affected by cytokines, we chose melanoma cells for further mechanism and in vivo studies to investigate the role of IL-4 in melanoma growth." (PMID 26993600, 2016). "Therefore, in the present study, to evaluate the role of IL-4 in skin tumor growth, we investigated whether overexpression of IL-4 inhibits melanoma cell and tumor growth through modulation of p21-mediated STAT6 pathways." (PMID 26993600, 2016). "In addition, IL-4 is found to promote tumor metastasis in B16 melanoma mouse model." (PMID 25208941, 2014). "Increased levels of IL-4, along with GM-CSF and dermcidin (DCD), have been recognized as significant biomarkers in early-stage melanoma." (PMID 40636453, 2025). "For example, serum IL-1β, IL-4, IL-6, IL-10, GM-CSF, TNF-α, and sPD-L1 has significant sex-related predictive effects on OS in patients with melanoma or non-small cell lung cancer treated with ICIs." (PMID 39085893, 2024). "Serum IL-1β, IL-4, IL-6, IL-10, GM-CSF, TNF-ɑ, and sPD-L1 had a significant sex-related predictive impact on ORR, PFS and OS in melanoma and NSCLC patients treated with ICIs." (PMID 38443899, 2024). "Along with the Breslow thickness, the Melanoma CDSS includes features such as the relative number of tumors infiltrating L-BCL2+ and serum levels of IL-4 or IL-6, all of which have been reported to be important risk factors for melanoma progression." (PMID 37046835, 2023). "Recent studies have revealed that IL7 plays a significant role in glioma, melanoma and leukemia by contributing to anti-tumor effects through the release of cytokines, including IFNG, IL1A, IL1B, TNF, IL2 and IL4." (PMID 37958451, 2023).
melanoma (continued). "In the 4T1 tumor and B16 melanoma models, not only the production of IgG and the secretion of cytokines, such as IFN-γ, interleukin-4 (IL-4), and TNF-α, were upregulated; the effector T cell CD8+ was activated, and the number of Tregs was reduced." (PMID 34842684, 2021). "The A375-A2-ESO human melanoma cells, ESO-T cells, and IL-4/IL-13-polarized MDMs were mixed at a 2:2:1 ratio and placed in a 3D tumor organoid culture mimicking TME." (PMID 34112755, 2021). "In the interleukin-4 and interleukin-13 signaling pathway, CXCL8 and MMP3 have published roles in melanoma growth and metastasis." (PMID 35008167, 2021). "We have developed a prognostic equation that considers the serum IL‐4, GM‐CSF, and DCD levels, along with the Breslow thickness to accurately classify melanoma outcome in early‐stage (I‐II) patients." (PMID 32485045, 2020). "The results show that in early‐stage melanoma patients, serum levels of the cytokines IL‐4, GM‐CSF, and DCD together with the Breslow thickness are those that best predict melanoma metastasis." (PMID 32485045, 2020). "Next, in vitro generated TAM from SK- BR- 3 TCM and the cytokines IL-4, IL-10, and M-CSF were compared to TAM derived from melanoma tumor tissue using the same flow panel and gating strategy." (PMID 31138333, 2019). "A lot of researchers have reported about the imbalance of cytokines in patients with melanoma - statistically low levels of IL-2 and IFN-γ and high levels of IL-4, IL-6 and IL-10 that reflects the imbalance between Th1/Th2 immune responses." (PMID 29849947, 2018). "Increased nucleus phosphorylation of STAT6 by IL-4 was also abolished by transfection with p21 siRNA in SK-MEL-28 and B16F10 melanoma cells." (PMID 26993600, 2016). "Higher expression of IL-4, STAT6 and p21 in human melanoma tissue compared to normal human skin tissue was also found." (PMID 26993600, 2016). "IL-4-increased activity of STAT6 by IL-4 was also abolished by transfection with p21 siRNA in SK-MEL-28 and B16F10 melanoma cells." (PMID 26993600, 2016). "But, inhibition of cell growth by higher expression of p21 response to IL-4 was abolished by transfection with p21 siRNA in SK-MEL-28 and B16F10 melanoma cells." (PMID 26993600, 2016). "We analyzed expression of IL-4, STAT6 and p21 in human melanoma tissues (Stage II–IV) and normal tissues by immunohistochemistry analysis." (PMID 26993600, 2016). "IL-4, STAT6 and p21 are concomitantly and progressively expressed in human melanoma tissues in a cancer stage dependent manner." (PMID 26993600, 2016). "To determine the relationship between p21 expression and SK-MEL-28 and B16F10 melanoma cells growth and STAT6 activity in the inhibitory effects of IL-4, we transfected SK-MEL-28 and B16F10 melanoma cells with p21 siRNA using a transfection agent." (PMID 26993600, 2016). "Our present results showed that expression of IL-4 and IL-4Rα in SK-MEL-28 and B16F10 melanoma cells were increased." (PMID 26993600, 2016). "We found that IL-4 untreated SK-MEL-28 and B16F10 melanoma cells showed lower constituted activation of STAT6 in SK-MEL-28 and B16F10 melanoma cells." (PMID 26993600, 2016). "Our data demonstrated that consistent with cancer cell growth inhibition, IL-4 induced DNA binding activity of STAT6 and nucleus phosphorylation of STAT6 were increased in a B16F10 melanoma cell and melanoma tumor model." (PMID 26993600, 2016). "In the present study, we found that IL-4 overexpression inhibited cell growth of cultured SK-MEL-28 human melanoma cells and B16F10 murine melanoma cells in vivo through p21-mediated activation of STAT6." (PMID 26993600, 2016). "To evaluate the significance of interleukin 4 (IL-4) in tumor development, we compared B16F10 melanoma growth in IL-4-overespressing transgenic mice (IL-4 mice) and non-transgenic mice." (PMID 26993600, 2016).
melanoma (continued). "In vitro study, we found that overexpression of IL-4 significantly inhibited SK-MEL-28 human melanoma cell and B16F10 murine melanoma cell growth via p21-mediated activation of STAT6 pathway as well as increased expression of apoptotic cell death proteins." (PMID 26993600, 2016). "Agreed with the increment of DNA binding activity of STAT6, the phosphorylation of STAT6 in nuclei was increased by IL-4 treatment in SK-MEL-28 and B16F10 melanoma cells." (PMID 26993600, 2016). "PPP1R14A was shown in human pancreatic and melanoma tumor cell lines to positively regulate Ras/MAPK signaling, which are also involved in IL-4 induced signaling cascades." (PMID 23110343, 2012). "Here we compare the potential therapeutic benefit of transduction with IL-2 or IL-4 alone, and combined IL-2 + IL-4 in B16F10 cells, a murine malignant melanoma of poor immunogenicity." (PMID 8679459, 1996). "Both FL/GM-DCs and GM/IL4-DCs were more effective in the MC38 model, whereas GM/IL4-DCs failed to inhibit tumor growth in the B16F10 melanoma model." (PMID 40977690, 2025). "Melanoma-derived soluble factors and metabolites, such as TGF-β, IL-10, IL-4, and IL-13 May contribute to this shift toward acquisition of pro-tumorigenic features." (PMID 38533720, 2024). "Another phase II study also concluded no benefit of IL-4 treatment at the maximum tolerated dose for melanoma or renal cell carcinoma." (PMID 37455828, 2023). "Two models were obtained to predict metastasis (including “all patients” or only patients “at early stages of melanoma”), and a series of attributes were seen to predict the progression of metastasis: Breslow thickness, infiltrating BCL-2 expressing lymphocytes, and IL-4 and IL-6 serum levels." (PMID 37046835, 2023). "Thus, while melanoma cell-derived Activin-A supports myeloid cell infiltration at the expense of CTL recruitment to the tumor site, IL4 is dispensable for Activin-A-induced tumor growth advantage." (PMID 35580932, 2022). "A study of individual CSF samples from 22 patients with melanoma brain metastases and 5 disease-free controls found that Chemokine CCL22 and cytokines IL-1α, IL-4, and IL-5 were reduced in most samples, whereas a subset of molecules including CXCL10, CCL4, CCL17, and IL8 increased expression." (PMID 36527157, 2022). "Our data showed that the IL-4 polarized M2 macrophages, which express a phenotype similar to the “M2-like” phenotype of TAMs, were the most efficient in taking up the IL-13-LCL in vitro, compared to M1 (antitumoral) macrophages and to B16.F10 melanoma cells." (PMID 35450036, 2022). "In addition, IL-4 production by Vγ1 T cells impairs the cytotoxic properties (e.g., NKG2D and perforin) of antitumoral Vγ4 T cells on melanoma cells." (PMID 34298791, 2021). "Remarkably, we found a prognostic plane involving the serum levels of IL‐4, GM‐CSF, and DCD in conjunction with the Breslow thickness that could accurately classify subjects according to their melanoma outcome." (PMID 32485045, 2020). "In line with previous findings, early‐stage (I or II) melanoma patients that developed metastasis had significantly higher levels of serum IL‐4 and IL‐6 than patients who did not develop metastasis during the follow‐up." (PMID 32485045, 2020). "Furthermore, these data clearly pointed to the cytokines IL‐4, GM‐CSF, and DCD as the most powerful biomarkers in predicting melanoma metastasis in conjunction with the Breslow thickness." (PMID 32485045, 2020). "The current study including a new cohort of melanoma patients revealed that DCD is a marker of metastatic progression, although other serological parameters appear to have greater predictive potential than DCD, such as IL‐4 and GM‐CSF." (PMID 32485045, 2020). "Recently, IL-4 and Th2 inflammation was shown to promote B16F10 melanoma metastasis." (PMID 29403003, 2018). "However, the expression of Bcl2 was decreased by the treatment of IL-4 in SK-MEL-28 and B16F10 melanoma cells." (PMID 26993600, 2016).
melanoma (continued). "In our previous study on melanoma, we observed a negative impact on survival for the patients who produced IL-4 reactive to Melan-A." (PMID 26500775, 2015). "In addition, GM-CSF+IL-4-modulated DDC and LC were superior inducers of anti-melanoma CD8+ effector T cells, which were shown to exhibit increased functional avidity." (PMID 23875023, 2013). "At the same time, IL-4 has been shown to suppress the growth of melanoma cell lines and enhance their immunogenicity, thus enhanced IL-4 expression would not be expected to enhance melanomagenesis." (PMID 22745913, 2012). "In cytokine release assays, CD8+ clones released interferon-γ but not IL-4 (data not shown) in response to stimulation with melanoma lines consistent with the acquisition of a Tc1 phenotype." (PMID 16819544, 2006). "Finally, experiments in different mouse tumor models (melanoma, lung, and colon cancer) showed that PGD2 produced by T follicular helper (Tfh) cells can recruit Th2 cells within the tumor and stimulate their production of IL-4, thus promoting tumor growth." (PMID 41368640, 2025). "Furthermore, inflammatory TH2-biased conditions such as IL-10, IL-4, VEGF and FoxP3+ Tregs that support class switching to IgG4 rather than IgE, and elevated IgG4 levels have been reported in different tumors including melanoma." (PMID 27471625, 2016). "There are several other cytokines such as IL-4 and IL-13 that are known to have a negative impact on survival and which would have been interesting to examine here, especially as we previously found that IL 4 was relevant in melanoma." (PMID 26500775, 2015). "Three different DC lines cultured for 7–9 days in medium containing GM-CSF and IL-4 (CD14−, CD36+ and CD83−) showed higher levels of intracellular MC1R than short time cultured monocytes, comparable to that observed in the low MC1R expressing BL melanoma cell line." (PMID 12177778, 2002). "To determine whether the reduced degranulation of iNKT cells affected cytokine production, we stimulated iNKT cells with αGC-unloaded/loaded THP-1 CD1d cells and analyzed the supernatant for secreted IFN-γ and IL-4 levels after 4 days of culture, in the presence/absence of melanoma cells." (PMID 37444608, 2023). "On the systemic level, we detected tapeworm-specific production of IL-4, IL-10, and IFN-γ by splenocytes isolated from infected mice, but no melanoma-specific cytokine response was observed." (PMID 38571957, 2024). "Supernatant from CD8+ CTL793 after 24–48 hr of stimulation with autologous melanoma cells WM793 contained significant amounts of IFN-γ, TNF-α, and GM-CSF, but not IL-2 or IL-4 (data not shown, except for IFN-γ release in Table II)." (PMID 16281981, 2005). "Furthermore, in the B16F10 melanoma model, PGD2 was able to restrain IFNγ production, but not IL-4, by invariant NKT cells, reducing the protective effects of the iNKT ligand alpha-GalCer against experimental metastasis, in vivo." (PMID 41368640, 2025). "Finally, although this study observed changes in IL-35, IL-4, and IL-13 levels after knockdown of EBI3, the specific role of these cytokines in melanoma was not analyzed in detail." (PMID 39726752, 2024). "In Braf/Pten melanoma-draining LNs, TSLP promoted not only GATA3+ Th2 cells, but also GATA3+ Tregs expressing a specific signature including ST2, CCR8, ICOS, PD-1, CTLA-4, OX40, and IL-10 — but not Th2 cytokines IL-4 and IL-13." (PMID 36107619, 2022). "Finally, the expression values of IL-4, xCT, and YM1 in control or melanoma tissues derived from metastatic (iMet model) and non-metastatic (iHRAS model) tissues were compared using Gene Expression Omnibus (GEO) data (GSE29074)." (PMID 33959512, 2021).